CCL21 (C-C motif chemokine ligand 21)
Description:
Binds to atypical chemokine receptor ACKR4 and mediates the recruitment of beta-arrestin (ARRB1/2) to ACKR4. Binds to chemokine receptor CCR7. Does not bind to chemokine receptor CXCR3. Binds to G protein-coupled receptor GPR174 (By similarity). Inhibits hemopoiesis and stimulates chemotaxis. Chemotactic in vitro for thymocytes and activated T-cells, but not for B-cells, macrophages, or neutrophils. Shows preferential activity towards naive T-cells. May play a role in mediating homing of lymphocytes to secondary lymphoid organs.
Synonyms: SLC; SCYA21; exodus-2; TCA4; CKb9; 6Ckine; ECL
Tractability: Antibody: its Gene Ontology location is reachable by antibodies, with high confidence; UniProt places it where antibodies can reach, with medium confidence; UniProt predicts a signal peptide or a membrane-spanning region.
Gene: Protein-coding gene on chromosome 9 (34,709,005 to 34,710,167, reverse strand). Ensembl gene ENSG00000137077.
Subcellular location: Secreted
Pathways (Reactome):
Signal Transduction: Chemokine receptors bind chemokines; G alpha (i) signalling events
Gene Ontology:
Molecular function: chemokine activity; chemokine receptor binding; protein binding; CCR chemokine receptor binding; CCR7 chemokine receptor binding; cytokine activity
Biological process: CCL21-activated CCR7 signaling pathway; cell chemotaxis; cellular response to prostaglandin E stimulus; dendritic cell chemotaxis; establishment of T cell polarity; G protein-coupled receptor signaling pathway; mesangial cell-matrix adhesion; negative regulation of dendritic cell apoptotic process; negative regulation of leukocyte tethering or rolling; positive regulation of actin filament polymerization; positive regulation of canonical NF-kappaB signal transduction; positive regulation of cell adhesion mediated by integrin; positive regulation of cell motility; positive regulation of cell-matrix adhesion; positive regulation of ERK1 and ERK2 cascade; positive regulation of filopodium assembly; positive regulation of JNK cascade; positive regulation of myeloid dendritic cell chemotaxis; positive regulation of neutrophil chemotaxis; positive regulation of phosphatidylinositol 3-kinase/protein kinase B signal transduction; positive regulation of phospholipase C/protein kinase C signal transduction; positive regulation of pseudopodium assembly; positive regulation of T cell migration; release of sequestered calcium ion into cytosol; ruffle organization; and 21 more
Cellular component: extracellular region
Genetic constraint (gnomAD): Loss-of-function variants: 12 observed, 17.31 expected, observed/expected ratio (o/e) 0.69, 90% interval 0.44 to 1.12. The upper end of that interval is the gene's LOEUF score, 1.12, which puts it in group 4 of 6, group 1 being the genes least tolerant of losing a copy. Missense variants: 155 observed, 172.74 expected, observed/expected ratio (o/e) 0.9, 90% interval 0.79 to 1.02. Synonymous variants: 64 observed, 65.61 expected, observed/expected ratio (o/e) 0.98, 90% interval 0.8 to 1.2.
Homologues: Orthologues: chimpanzee CCL21 (100% identical), macaque CCL21 (92% identical), rabbit CCL21 (79% identical), pig CCL21 (75% identical), guinea pig CCL21 (74% identical), mouse Ccl21b (71% identical), mouse Ccl21d (71% identical), mouse Ccl21e (71% identical), mouse Ccl21f (71% identical), mouse Ccl21a (70% identical), dog CCL21 (69% identical), rat Ccl21 (66% identical), and 1 more. Paralogues in human: CX3CL1 (34% identical), CCL4 (28% identical), CCL11 (27% identical), CCL19 (26% identical), CCL25 (26% identical), CCL7 (26% identical), CCL16 (25% identical), CCL2 (25% identical), CCL23 (25% identical), CCL24 (25% identical), CCL26 (25% identical), CCL4L2 (25% identical), and 14 more.
Diseases named in the same sentence as CCL21 in open-access papers:
CCL21 is named in the same sentence as 260 diseases in open-access papers, as found by Europe PMC text mining. Sharing a sentence is not in itself a finding about the gene and the disease. The quoted sentences say what the papers report.
breast cancer (70 papers, 2008 to 2025). A primary or metastatic malignant neoplasm involving the breast. "In human breast cancer, higher CCL21 expression levels are associated with increased infiltration of CD8+T cells and reduced long-term recurrence rates." (PMID 40149008, 2025). "Chemokine receptor CCR7 and its ligand CCL21 are implicated in the metastasis of breast cancer to the lymph nodes." (PMID 34298676, 2021). "The enhanced migration capability of in vitro generated breast cancer tumor and normal cell fusions is also linked to chemokine receptor CCR7 and a ligand CCL21 interaction that is associated with the migration of breast cancer cells to the lymph nodes." (PMID 32182935, 2020). "It is important to note that high CCL21 expression in tumor cells, for example in bladder cancer and breast cancer, is associated with an increased proliferation, number of metastases and a suppressive immune reaction." (PMID 27369431, 2016). "Because the CCL21/CCR7 axis has been associated with lymph node metastasis of breast cancer (for review see:) cell migration studies were conducted by using the 3D-collagen matrix migration assay." (PMID 23667660, 2013). "Although CCR7 is the primary chemokine receptor associated with lymph node metastasis, CXCR3, which may bind with moderate affinity to CCL21 in mice, has also been linked to lymph node chemotaxis in breast cancer and melanoma in a murine model." (PMID 35203305, 2022). "Since CCL21 has been associated with lymph node metastases in breast cancer, these findings likely indicate that the fusion of CCL21-insensitive cancer cells could give rise to CCL21-sensitive cancer hybrid cells." (PMID 34503305, 2021). "Because the CCL21/CCR7 axis has been linked to metastatic spreading of breast cancer to lymph nodes we conclude from our data that cell fusion could be a mechanism explaining the origin of metastatic cancer (hybrid) cells." (PMID 23667660, 2013). "Because the CCL21/CCR7 axis has been associated with lymph node metastasis formation of breast cancer we conclude that cell fusion between breast cancer cells and breast epithelial cells exhibiting stem cell properties is a possible mechanism how metastatic cancer hybrid cells can originate." (PMID 23667660, 2013). "Finally, we investigated whether the expression of CCR7 and CCL21 could be linked to EMT in human breast cancer." (PMID 25961925, 2016). "For example, in breast cancer, CCR7 is highly expressed in tumor cells and metastatic sites, and CCR7/CCL21 signaling is associated with lymph node metastasis and tumor progression." (PMID 40038879, 2025). "The promotion of cancer cell migration into micro lymphatic capillaries by CCL21/CCR7 has also been observed in breast cancer and esophageal squamous cell carcinoma." (PMID 36829431, 2023). "Research has explored the therapeutic potential of CCL21 in the context of breast cancer (BRCA), suggesting its significance in cancer treatment." (PMID 37944262, 2023). "Recently, we reported that TGFβ1 stimulated breast cancer cells with mesenchymal properties to migrate in a targeted fashion towards the lymphatic system via CCR7/CCL21-mediated chemotaxis, similar to dendritic cells during inflammation." (PMID 38055067, 2023). "CCL21 mediates intravasation mostly into different lymphatic vessels and the progression of many different types of cancer, including breast cancer." (PMID 36661524, 2023). "A recent study showed that breast cancer cells expressing CCL21 induced CXCL13 secretion from stromal cells through the recruitment of innate lymphoid cells to the tumor microenvironment." (PMID 37958571, 2023). "Previously, we reported that TGFβ1-induced EMT promotes lymphatic dissemination of breast cancer cells by activating CCL21/CCR7-mediated chemotaxis." (PMID 38055067, 2023). "This TGF-β1-mediated lymphatic migration was associated with CCL21 release from lymphatic endothelial cells and chemotaxis of CCR7-expressing breast cancer cells." (PMID 35203305, 2022).
breast cancer (continued). "CCL21 was commonly DE in all the cells after curcumin treatment, indicating its role in immunomodulating breast cancer cells." (PMID 34981672, 2022). "Oncogenic genes like FAM83D, CTDSP1, and SAPCD2 were downregulated in all three cells, and tumor suppressor genes (TSGs) like ZNF292, ANKRD12, NKAPL, and CCL21 were upregulated in all three breast cancer cells upon curcumin treatment." (PMID 34981672, 2022). "In breast cancer, TGF-β1 activates a Smad protein-linked pathway, resulting in EMT phenotype and lymphatic migration in response to CCL21 release from lymphatic endothelial cells and chemotaxis of CCR7-expressing breast cancer cells." (PMID 35203305, 2022). "CCR7, CCL21 and miR-let-7a were detected in both breast cancer cell lines and patient breast cancer tissue." (PMID 35203305, 2022). "In vitro studies on breast cancer cell lines revealed that CCL21 stimulation enhanced cell invasive properties, an EMT phenotype, upregulated Slug and N-cadherin with concomitant reduction in E-cadherin." (PMID 35203305, 2022). "Increased VEGF-C and CCR7 expression in breast carcinoma tissue and increased CCL21/CCR7 activation in lymphatic endothelial cells promoted lymphatic endothelial cell proliferation and lymph node metastasis of the CCR7-expressing breast cancer cells." (PMID 35203305, 2022). "According to The Cancer Genome Atlas (TCGA) database, analyses on breast cancer shows that CCL21 expression is positively correlated with T cells." (PMID 34160019, 2021). "One of the modeling studies on breast cancer treatment was the intra-tumoral administration of (CCL21) and interferon γ (IFN-γ) combination to enhance tumor specific T-cell recruitment in the breast cancer microenvironment." (PMID 34160019, 2021). "The TGF-β pathway has also been shown to induce expression of CCL21 in lymphatic endothelial cells EC_PROX1 promoting the migration of tumour cells towards the lymphatic endothelial cells in breast cancer." (PMID 34238352, 2021). "In human breast cancer cells, the stimulation of intracellular actin polymerization by CCL21 increases the motility of cancer cells and thus favors metastasis." (PMID 34160019, 2021). "CCR7 chemokine receptor binds to the ligand CCL19/CCL21 and promotes lymphogenesis and metastasis in breast cancer." (PMID 34544443, 2021). "We found that CCL21/CCR7 expression by breast cancer cells promoted tumor-induced lympho-vascular recruitment in vivo and VEGF-C production by LECs in vitro." (PMID 33668160, 2021). "Researchers have found that CCL21/CCR7 chemokine axis not only induced lymphangiogenesis in breast cancer, but also promoted breast cancer cells migration and metastasis." (PMID 32195260, 2020). "The corresponding ligands CXCL12 and CCL21 are present at elevated levels in lymph nodes, lung, liver and bone marrow—preferred distant metastatic sites of breast cancer." (PMID 32547940, 2020). "A schematic illustration of CCR7 binding to the cognate ligands CCL19/CCL21 to induce several signaling transduction pathways in breast cancer is shown in." (PMID 32340161, 2020). "Experiments on breast cancer cells show that chronic hypoxia only increases CCL21/SLC expression at the mRNA level, while at the protein level the expression of this chemokine is decreased." (PMID 32781743, 2020). "Chemokine (C-C Motif) Ligand 21 (CCL21), a chemokine basically expressed by lymphatic endothelial cells, has been suggested to attract melanoma and breast cancer cells expressing its receptor Chemokine (C-C Motif) Receptor 7 (CCR7)." (PMID 31963450, 2020). "The interaction between CCR7 and CCL21 has been shown to improve the immunogenicity of CCR7-expressing breast cancer cells." (PMID 32340161, 2020). "The corresponding ligands on the other hand, CXCL12 and CCL21, are present at elevated levels in lymph nodes, lung, liver, and bone marrow—preferred distant metastatic sites of breast cancer." (PMID 31533220, 2019).
breast cancer (continued). "A recent study suggested that CCL21/CCR7 chemokine axis expressed on breast cancer cells interacts with VEGFR3 present on LECs to induce tumor-dependant lymphatic vascular recruitment and thereby lymphangiogenesis in breast cancer." (PMID 29455658, 2018). "Expression of the CCL21 receptor CCR7 is also increased in breast cancer cells upon TGF‐β‐induced EMT, which facilitates breast cancer cell migration toward CCL21‐positive, draining lymphatic vessels in mice, in a DC‐like fashion." (PMID 28599100, 2017). "As other cancer cells, mammary carcinoma cells are able to metastasize into lymph nodes in a process involving the CCL21/CCR7 axis." (PMID 28416768, 2017). "Tumor growth inhibition was evidenced upon CCL21 expression in colon carcinoma and murine models of melanoma as well as mammary carcinoma." (PMID 28416768, 2017). "In the context of breast cancer, chemokines have been implicated in promoting the malignant phenotype: CXCL3, CXCL12, CXCL13, CCL21 and CCL5 are associated with tumour progression and metastasis in breast cancer." (PMID 27335323, 2016). "Using the 4T1.2 syngeneic model of breast cancer we showed that ILC3 recruitment to primary tumors is CCL21-dependent." (PMID 27882334, 2016). "Therefore, the objective of the present study was to investigate whether CCL21/CCR7 signaling promotes breast cancer-associated lymphangiogenesis through CCR7-dependent stimulation of VEGF-C secretion followed by LECs activation towards the development of new lymphatic vessels." (PMID 25744065, 2015). "Overall, these findings suggest that CCL21/CCR7 pair has the potential to regulate VEGF-C expression/secretion in the analyzed breast cancer cell line models." (PMID 25744065, 2015). "We demonstrated that the expression of CCL21/CCR7 by breast cancer cells has the ability to promote tumor-induced lymph-vascular recruitment in vivo." (PMID 25744065, 2015). "By utilizing CCR7 and CCL21 gene manipulated breast cancer cell implants into orthotopic sites of nude mice, lymphatic vessel formation was assessed through quantitative real-time PCR, immunohistochemistry and immunofluorescence assays." (PMID 25744065, 2015). "Given the recent evidence suggesting the implication of C-C chemokine ligand 21/chemokine receptor 7 (CCL21/CCR7) in lymph node metastasis, the aim of our study was to define the role of this chemokine pair in breast cancer-associated lymphangiogenesis." (PMID 25744065, 2015). "By utilizing CCR7 or CCL21 gene manipulated breast cancer cell implants in vivo we have shown that the analyzed chemokine pair promotes host lymphatic vessel recruitment and growth." (PMID 25744065, 2015). "When MCF-7 breast cancer cells were made to express high levels of CCL21, increased tumor immunogenicity was noted via HLA and TAP-1 expression increases." (PMID 24762633, 2014). "Here we investigated M13HS hybrid cell lines, derived from spontaneous fusion events between M13SV1-EGFP-Neo breast epithelial cells exhibiting stem cell characteristics and HS578T-Hyg breast cancer cells, concerning CCL21/CCR7 signaling." (PMID 23667660, 2013). "First, a higher expression of both CCR7 and CCL21 in malignant tissues than in their normal counterparts from breast cancer patients was observed." (PMID 22251626, 2012). "Further, their respective ligands CXCL12 and CCL21 are highly expressed in the target organs of breast cancer metastasis that can partly explain the metastatic pattern in breast cancer patients." (PMID 22481918, 2012). "A higher expression of CCL21 in malignant tissues than in their normal counterparts from breast cancer patients was discovered." (PMID 22251626, 2012). "In the present study, CCL21 expression in breast cancer cell lines and in breast cancer patients was evaluated." (PMID 22251626, 2012). "First, the expression of mRNA for CCR7 and its ligands CCL19 and CCL21 was confirmed in breast cancer cell lines and in malignant and normal tissues from breast cancer patients." (PMID 22251626, 2012).
breast cancer (continued). "Their respective ligands CXCL12/ SDF-1a and CCL21/6Ckine are highly expressed in organs representing the first destinations of breast cancer metastasis." (PMID 23905066, 2012). "The expression of CCR7, its ligand CCL21, and let-7a was detected in breast cancer cell lines and in breast cancer patient tissues." (PMID 22251626, 2012). "Further studies, using different techniques such as quantitative RT-PCR or protein extraction on frozen samples, will be needed to accurately assess the expression of CCL20 and CCL21 in primary breast cancer." (PMID 21624121, 2011). "They proposed that the ideal CCL21 concentration for CCR7 expression in breast carcinoma is 50-500 nmol/L." (PMID 21548969, 2011). "In addition, transfection of breast cancer MCF‐7 cells with CCL21 protein potentiated a range of functions of DCs, such as antigen uptake and presentation, migration, and antiapoptotic ability in vitro." (PMID 35702353, 2022). "The complete picture of the role and involvement of the CCL21/CCR7 pair in breast cancer is still undergoing development, but there are at least two areas in which this axis has been shown to be actively involved, including lymph nodes metastasis and immune response modulation." (PMID 34298676, 2021). "This impaired extravasation was also observed in vivo, where mut-CCL21 could reduce the number of metastatic lymph nodes in a breast cancer murine model." (PMID 34298676, 2021). "Therefore, CCL21 is known to improve immunogenicity in breast cancer in tandem with its receptor CCR7." (PMID 34160019, 2021). "Moreover, the effect of CCL21 availability to breast cancer cells, through PDPN expression by CAFs, was addressed." (PMID 28416768, 2017). "Moreover, CCR7 was shown to promote mammary cell tumorigenesis through amplification of stem-like cells which points to the key role played by the CCL21/CCR7 axis in the various steps of mammary tumor evolution." (PMID 28416768, 2017). "Furthermore, CCL21/CCR7 was also found to promote cancer cell migration into microlymphatic vessels in breast cancer, pancreatic tumor, lung adenocarcinoma, and esophageal squamous cell carcinoma." (PMID 25798926, 2015). "Muller and colleagues have shown that chemokine receptors CXCR4 and CXCR7 are highly expressed in human breast cancer specimens, while their corresponding ligands CXCL12/SDF-1alpha (stromal cell-derived factor) and CCL21/6Ckine showed peak levels in primary breast cancer destination sites." (PMID 22746994, 2012). "In the present study, we assessed the expression of CCR6, CCR7 and their ligands CCL19, CCL20 and CCL21 using immunohistochemistry in a series of tumors prospectively collected from patients with loco-regional breast cancer treated at the Centre Léon Bérard in 1996 and 1997." (PMID 21624121, 2011). "While CXCR4 and another chemokine receptor, CCR7, are highly expressed on the surface of human breast cancer cells, CXCL12 and a CCR7 ligand, CCL21, are highly expressed in lymph nodes, bone marrow, lung and liver, which form the common metastatic destinations of breast cancer." (PMID 19787093, 2008). "Similarly, in an orthotopic mouse model of breast cancer, intratumoral administration of CCL21 significantly increased the proportion of T cells, NK cells, and DCs within the tumor, reduced the size of the tumor and extended the survival time of tumor‐bearing mice." (PMID 35702353, 2022). "Our study adds new elements to the multifaceted role of CCL21/CCR7 chemokine pair in mammary malignancy by revealing a novel role of this chemokine axis in breast cancer-associated lymphangiogenesis that might be relevant to future therapies." (PMID 25744065, 2015). "In addition, CCL21 also induced breast carcinoma cell migration and basement membrane invasion." (PMID 21548969, 2011). "For instance, CXCL12 and SLC (CCL-21) bind to CXCR4 and CCR7 receptors on breast cancer cells, respectively, promoting tumor cell migration to the lymphatic system along a chemotactic gradient." (PMID 40084140, 2025).